RNU2-59P (RNA, U2 small nuclear 59, pseudogene)
Gene: Small nuclear RNA gene on chromosome 10 (101,364,845 to 101,365,035, reverse strand). Ensembl gene ENSG00000222414.
Homologues: Orthologues: chimpanzee U2 (100% identical), pig U2 (86% identical), guinea pig U2 (82% identical), guinea pig U2 (54% identical), dog U2 (28% identical). Paralogues in human: U2 (89% identical), U2 (88% identical), RNU2-36P (88% identical), RNU2-4P (86% identical), RNU2-2 (86% identical), RNU2-6P (86% identical), RNU2-3P (85% identical), RNU2-26P (84% identical), RNU2-57P (84% identical), RNU2-64P (84% identical), RNU2-8P (84% identical), RNU2-61P (83% identical), and 66 more.